BCL2 (BCL2 apoptosis regulator)
Diseases named in the same sentence as BCL2 in open-access papers (continued):
Sharing a sentence is not in itself a finding about the gene and the disease.
cancer (continued). "One specific method involves the overexpression of anti-apoptotic proteins like Bcl-2, which can lead to the development of drug-resistant cancer cell lines." (PMID 38691208, 2024). "They further identified that costunolide induces apoptosis in these cancer cells by amplifying the expression of the pro-apoptotic protein Bax while downregulating anti-apoptotic proteins Bcl-2 and Bcl-xL." (PMID 38529189, 2024). "NF-κB down regulation brings about a decrease in the levels of anti-apoptotic proteins such as Bcl-2 and so promote apoptosis in the cancer cells." (PMID 39467702, 2024). "Drugs inhibiting anti-apoptotic Bcl-2 proteins are in clinical phases, offering the potential for more effective and less toxic cancer treatments." (PMID 39594587, 2024). "ABT737 can promote the apoptosis of cancer cells by competitively inhibiting theanti-apoptotic molecule BCL2, which makes ABT737 available in the treatment of PTC." (PMID 38488525, 2024). "Numerous studies have demonstrated that elevated levels of pro-survival proteins, including BCL-xL, MCL-1, and BCL-2, are frequently observed in cancers and contribute to drug resistance." (PMID 38898061, 2024). "The balance between Bcl-2 and Bax levels serves as a crucial indicator of cancer cell apoptosis induced by chemotherapy and radiation." (PMID 39308674, 2024). "Because of its role as an inhibitor of apoptosis, elevated levels of Bcl-2 expression have been detected in various human cancers such as breast, cervical, non-small cell lung, and prostate." (PMID 38317891, 2024). "BH3 mimetics which made it possible to target interactions of Bcl-2 proteins equipped humanity with new powerful options to stand against cancer." (PMID 39048751, 2024). "Previous studies have shown that the chimeric transcription factor EWS-FLI1 induces BCL-2 expression, promoting cancer cell survival." (PMID 39199601, 2024). "Interactions between BCL-2 proteins and calcium signaling are particularly important in the context of cancer cells." (PMID 39769488, 2024). "Furthermore, it was identified that the degradation of IκBα could be inhibited by PL and then suppressed the NF-κB activation and its translocation to the nucleus for function, which caused the downregulation of the anti-apoptosis protein BCL2 expression on various cancer cells." (PMID 38397018, 2024). "For autophagy, JNK regulates autophagy by affecting autophagy‐related genes and induces autophagy through Bcl‐2 phosphorylation, which contributes to cancer cell survival." (PMID 38800967, 2024). "For example, co-cultured umbilical cord-derived MSCs with hepatocarcinoma cell line HepG2 downregulated the protein expression of AFP, Bcl-2, and survivin and accelerated cancer cell apoptosis, which was related to the apoptosis signal pathway." (PMID 38660138, 2024). "Cancer cells typically evade cell death by upregulating antiapoptotic proteins like BCL-2 or inhibiting pro-apoptotic proteins such as Casp9." (PMID 39005932, 2024). "As key regulators of apoptosis, MCL-1 and BCL-2 are survival factors and thus considered ideal cancer targets." (PMID 38008859, 2024). "Anti-apoptotic Bcl-2 familymember Mcl-1 has emerged as a targetof significant interest for the treatment of cancer." (PMID 39102508, 2024). "Several mutations were examined for their potential contributions to cancer initiation and progression, with their deleterious effects on the structure and function of Bcl-2 thoroughly characterized." (PMID 39840282, 2024). "In many cancers, increased levels of antiapoptotic proteins such as Bcl‐2 and Bcl‐xL prevent the activation of proapoptotic proteins, promoting cell survival and resistance to apoptotic signals." (PMID 39239068, 2024).
cancer (continued). "Together with our results, these data strongly indicate the existence of a bi-directional regulatory loop in cancer involving Bcl-2 and YAP." (PMID 38755629, 2024). "Venetoclax, a BCL-2 antagonist, induces apoptosis in cancer cells overexpressing BCL-2 and is approved for patients contraindicated for frontline treatment with kinase inhibitors." (PMID 39026380, 2024). "Navitoclax displayed strong efficacy against a range of cancers with high levels of BCL-2 and BCL-xL expression, most notably chronic lymphocytic leukemia (CLL), and lymphomas." (PMID 39497108, 2024). "Our data indicate that Bcl-2 inhibitors should be further investigated to counteract cancer-promoting mechanisms." (PMID 38755629, 2024). "In this instance, we were able to trigger apoptosis in cancer cells by upregulating Bax and caspases and downregulating BCL2 expression." (PMID 38592437, 2024). "Mcl-1 gene, a homologous of the BCL-2 gene, encodes the full-length MCL-1 protein and is one of the most amplified genes in malignant tumors 38-40." (PMID 38706892, 2024). "Lycopene has shown a chemo-preventive effect by inhibiting the NF-κB pathway and Bcl2, which further stops cancer proliferation in HCT116 and SW480 cell lines of colorectal carcinoma." (PMID 39246660, 2024). "The increased expression of Bcl-2 has been established to inhibit apoptosis and enhance cell viability in cancer." (PMID 38542202, 2024). "The combination of MDM2 and BCL2 inhibitors is also being explored in several types of cancer cells." (PMID 39144622, 2024). "Apoptosis in cancer cells was aided by the treatment with Xn because it decreased the expression of Bcl-2 and Survivin." (PMID 39421029, 2024). "Anti-apoptotic proteins, like Bcl-2 and Bcl-XL, are often overexpressed in cancer, leading to an anti-apoptotic phenotype that allows cancer cells to evade cell death." (PMID 39518013, 2024). "Cancer cells that are resistant to PDT often exhibit elevated levels of the anti-apoptotic protein Bcl-2, which functions to shield them from PDT-induced phototoxicity." (PMID 39494340, 2024). "The overexpression of proto-oncogene Bcl-2 can lead to the formation of various human cancers, which results not only in the inhibition of apoptosis, but also causes the chemotherapy- and radiotherapy-resistance phenomena." (PMID 39065762, 2024). "Apoptosis is a critical mechanism in cancer therapy, with key therapeutic targets including anti-apoptotic proteins such as BCL2, which regulates mitochondrial membrane permeability to prevent apoptosis." (PMID 39850823, 2024). "Polyphenols can induce programmed cell death (apoptosis) in cancer cells by activating caspase pathways and inhibiting antiapoptotic proteins, such as Bcl-2, which increases cancer cell mortality." (PMID 39407660, 2024). "Curcumin can regulate multiple signaling targets in cancer cells, leading to upregulation of the pro-apoptotic gene Bax and caspase cascade response and downregulation of the anti-apoptotic gene Bcl-2." (PMID 38313314, 2024). "Trop2 affects cancer cell apoptosis by upregulating Bcl2 and downregulating the expression of the pro-apoptotic protein Bax." (PMID 39236081, 2024). "Meloxicam, Aspirin, Indomethacin, and Celecoxib can down-regulate Bcl-2 expression and up-regulate Bax expression, thereby inducing apoptosis in cancer cells." (PMID 39598398, 2024).
cancer (continued). "Multidrug resistance (MDR) in cancer cells can be overcome by selectively inhibiting Bcl-2, resulting in cell cycle arrest, senescence, and eventual cell death in response to radiotherapy and chemotherapy." (PMID 39840282, 2024). "The results indicate that LP treatment can increase the pro-apoptotic BAX protein level, while decreasing the anti-apoptotic Bcl-2 protein level in all cancer cell lines." (PMID 38258008, 2024). "We report the identification of a small molecule that exposes the Bcl-2 killer conformation and induces death in Bcl-2–expressing cancer cells." (PMID 38329389, 2024). "“Bcl-2 functional converters” are envisioned to function as targeted cancer therapeutics, exploiting the cancer-specific overexpression of Bcl-2." (PMID 38329389, 2024). "These NPs were used to deliver Bcl-2 siRNA, with the aim of inhibiting Bcl-2 protein synthesis and promoting apoptosis of cancer cells." (PMID 39065565, 2024). "For example, BCL-2 gene expression is elevated in over half of all cancers and XIAP is overexpressed in many tumors." (PMID 39007268, 2024). "BCL-2 (B-cell lymphoma 2) is an anti-apoptotic protein that plays a crucial role in cancer prognosis, particularly due to its influence on cell survival pathways and its ability to inhibit programmed cell death." (PMID 39685591, 2024). "Controlling caspase and Bcl-2 protein expression can inhibit the proliferation of cancer cells and induce apoptosis." (PMID 39410090, 2024). "For instance, small molecule inhibitors that selectively block anti-apoptotic proteins, such as Bcl-2 or Bcl-xL, have shown efficacy in preclinical models of cancer and are being evaluated in clinical trials for various malignancies." (PMID 39060849, 2024). "Cancer cells often overexpress proteins that prevent the apoptotic cascade from being activated, including Bcl-2 and related anti-apoptotic proteins such as Bcl-xL, Mcl-1, A1/Bf1 and Bcl-w." (PMID 39620145, 2024). "lanata to cause apoptosis in Saos2 cells is suggested by the downregulation of Bcl2 mRNA expression, which lends additional credence to its anti-cancer properties." (PMID 38738026, 2024). "Although venetoclax is a selective small-molecule Bcl-2 inhibitor, it is ineffective against cancer cells with high Mcl-1 levels, including MM." (PMID 39411073, 2024). "Navitoclax, a member of the B-cell lymphoma 2 (BCL-2) family of protein inhibitors, was shown to induce apoptosis in cancer cells by disrupting the interactions between BCL-2-like proteins and BH3 domains." (PMID 38271056, 2024). "This study demonstrates a novel approach to targeting Bcl-2 using BFC1108, a small molecule Bcl-2 functional converter that effectively induces apoptosis in Bcl-2–expressing cancers." (PMID 38329389, 2024). "Emerging therapies targeting Bcl2 family proteins, such as selective and pan-Bcl2 inhibitors, can potentially restore cellular death in cancer cells." (PMID 39554609, 2024). "Our findings would contribute to the broader discourse on the genetic underpinnings of cancer, illustrating how specific SNPs can alter key apoptotic regulators such as Bcl-2." (PMID 39840282, 2024). "Editing the BCL-2 gene using CRISPR-Cas9 in cancer treatment holds significant potential due to the role of the BCL-2 protein in promoting cancer cell survival." (PMID 38195537, 2024). "The same findings were observed, where downregulating Bcl-2 expression with antisense oligonucleotides increased apoptosis and urged cancer cells to be more sensitive to chemotherapy drugs." (PMID 38169388, 2024).
cancer (continued). "Apoptosis regulator BCL2 was downregulated in all carcinoma patients, as well as in the most benign and luminal A patients." (PMID 39000458, 2024). "Overexpression of Per2 in the carcinoma cell line leads to a downregulation of the Bcl2 gene and increased apoptosis." (PMID 38524161, 2024). "Some studies mentioned that Bcl-2 overexpression has adverse effects, and some studies have mentioned that Bcl-2 overexpression has better disease-free survival in some subtypes of carcinoma breast." (PMID 39252711, 2024). "Thereafter, Bax and Bcl2-mediated cytochrome c release was observed which further led to the caspase-activated killing of cancer cells." (PMID 38112935, 2023). "Navitoclax, a dual inhibitor of Bcl-2 and Bcl-xL, has been entered into a trial exploring convincing cancer therapies." (PMID 37612409, 2023). "The apoptosis was additionally confirmed by the increased expression of Bax, and Caspase 3, 8, 9 and Bcl-2 expression decreased in cancer cells." (PMID 37239974, 2023). "When Bcl-2 protein status was statistically assessed in cancer tissue, i.e., low expression versus high expression, an association between 5-FU@ZIF-8-SDG MOF gel and other formulation-treated groups was confirmed." (PMID 38004573, 2023). "Benzimidazole-LNPs induced cancer cell apoptosis, generated reactive oxygen species, and inhibited Bcl-2 expression in cancer cells while sparing toxicity among healthy HEK293T cells." (PMID 37622997, 2023). "BH3-mimetic drugs targeting related pro-survival BCL-2 proteins have also been developed for cancer therapy." (PMID 36755070, 2023). "The anti-cancer effect was applied by reducing Bcl-2 gene expression and enhancing caspase-3 gene expression as two signaling pathways of apoptosis induction." (PMID 36984763, 2023). "A study in cancer cell lines has shown that the anti-autophagic role of BCL2 requires direct interaction with CISD2." (PMID 36774344, 2023). "Bcl‐2 proteins are of particular interest due to their role in controlling apoptosis, a form of programmed cell death, and their overexpression in many cancers." (PMID 36564857, 2023). "Bcl-2 and Bax not only mediate radiotherapy-induced cell death, but also regulate cancer radiosensitivity." (PMID 37227584, 2023). "Targeting the intrinsic apoptotic pathway regulated by B-cell lymphoma-2 (BCL-2) antiapoptotic proteins can overcome the evasion of apoptosis in cancer cells." (PMID 37894324, 2023). "Some i-motifs on cancer and neurodegenerative disease genes, such as BCL2, KRAS, HRAS, and VEGF, were identified to regulate their gene expressions." (PMID 37658102, 2023). "We have previously shown that PPRHs are a valuable tool for gene silencing of relevant cancer targets such as dihydrofolate reductase, survivin, BCL2, TOP1, mTOR, MDM2, and MYC." (PMID 37108234, 2023). "Preclinical studies have demonstrated that statins seize the cell cycle and result in apoptosis of cancer cells by activation of Bax and deactivation of BCL-2." (PMID 37626743, 2023). "In this study, a series of indole-based compounds, U1–6, were designed, synthesized, and evaluated for their anticancer activity against Bcl-2-expressing cancer cell lines." (PMID 37834104, 2023). "In cancer cells, there is downregulation of pro-apoptotic proteins, such as Bax, and the overexpression of the anti-apoptotic protein, Bcl-2." (PMID 37623253, 2023). "This molecule works by inhibiting BCL-2, releasing pro-death proteins, and tipping the balance toward apoptosis in cancer cells." (PMID 37880389, 2023). "The high specificity of the interaction between ABCC1 and BCL-2 inhibitors suggests that efflux transporters hold great potential for the development of rational cancer treatments that involve newly approved small molecule inhibitors." (PMID 37726279, 2023).
cancer (continued). "Paxillin-mediated ERK activation using the phosphorylating Bcl-2 protein to increase its stability was shown to be responsible for paxillin-mediated cancer cell invasiveness." (PMID 37175948, 2023). "ABT-263, an orally available, selective inhibitor of the anti-apoptotic BCL-2 family proteins, including Bcl-2, Bcl-XL, and Mcl-1, has been demonstrated to possess antitumor activity against various types of cancers and is in clinical trials." (PMID 37063257, 2023). "This study investigated the effects of designed indole-based derivatives U1–6 on Bcl2-expressing cancer cell growth, apoptosis, and cell cycle progression." (PMID 37834104, 2023). "As shown in previous studies, dysregulation of Bax and Bcl-2 expression levels were indicated in various cancers, so that Bcl-2 as a stimulator cell cycle progression, had high-level expression." (PMID 37524903, 2023). "Consistent with previous studies, the attenuated-Beclin-1 levels in SH-SY5Y cells were correlated with the induction of apoptosis through interaction with Bcl-2 antiapoptotic members in cancer cells." (PMID 37529115, 2023). "As a class of representative drugs targeting apoptosis, the most fundamental process of cell survival, BCL-2 inhibitors have exhibited attractive characteristics in treating cancers with robust on-target efficacy, standing out in the era of novel drugs." (PMID 37894324, 2023). "Resisting cell death is one of the hallmarks of cancer and targeting cell death pathway (e.g., Bcl-2) has achieved encouraging results in clinics." (PMID 36864055, 2023). "In many cases of cancer, an increased expression of Bcl-2 helps the cancer cells to escape cell death, making Bcl-2 targeting an attractive anticancer strategy." (PMID 37240331, 2023). "Apoptosis in cancer cells was stimulated through the downregulation of Bcl-2 and survivin at the mRNA level, as well as modulations of Bcl-2, PARP, pro-caspase-3, and -9 at the protein level." (PMID 38104078, 2023). "In the current cancer cohort studies, bpb3 correctly predicted significant TF binding affinity changes at mutation blocks near the promoter of TERT and BCL2 genes in MN and FL, respectively." (PMID 37520692, 2023). "The B cell lymphoma-extra large (BCL-XL) protein is a member of the anti-apoptotic BCL-2 families which is responsible for signals opposing the stress conditions in cancer cells." (PMID 36839734, 2023). "S.M 50% EE treated HepG2 and Caco-2 cell lines significantly downregulated BCL2 expression level by more than ten folds in HepG2 cancer cells and by five folds in Caco-2 cancer cells (0.12 ± 0.001 for HepG2 and 0.28 ± 0.02 for Caco-2, respectively)." (PMID 36882428, 2023). "This was first demonstrated when lymphoid cells from BCL-2 transgenic mice were found to be resistant to several DNA damage-inducing anti-cancer agents and glucocorticoids." (PMID 36342579, 2023). "Lactobacillus casei and L. paracasei inhibit cancer by regulating the expression of Bcl-2 and caspase family proteins." (PMID 37705007, 2023). "This stable tRNA has a substantially increased efficiency necessary to support a pro‐cancer translation program including c‐Myc, BCL2, RAB31, JUNB and TRAF2." (PMID 37983928, 2023). "Decrease in the pro-apoptotic/pro-survival Bcl2 ratio, mainly due to upregulation of pro-survival Bcl-2 family members, is observed in several human cancers." (PMID 36195672, 2023). "BH3-mimetics are a series of small molecules that have been developed to exploit the binding specificities of anti-apoptotic BCL2 proteins in order to antagonize them and to promote the apoptotic death of cancer cells." (PMID 36831248, 2023). "Overexpression of Bcl2 is common in many types of human cancer and is highly correlated with therapy resistance." (PMID 37496993, 2023). "Small molecule inhibitors that mimic the BH3 domain and specifically bind to anti-apoptotic Bcl-2 proteins can disrupt this protein–protein interaction, resulting in apoptosis activation in cancer cells." (PMID 37834104, 2023).